ISG20 (interferon stimulated exonuclease gene 20)
Diseases named in the same sentence as ISG20 in open-access papers (continued):
Sharing a sentence is not in itself a finding about the gene and the disease.
cancer (continued). "ISG20 can play an important role in SARS-CoV-2 inhibition in certain types of cancer." (PMID 36177004, 2022). "Together, ISG20 may serve as a double-edged sword in viral prevention and cancer progression in certain types of cancer." (PMID 36177004, 2022). "Among these, higher expression of ISG20 was associated with a longer OS in CESC and SKCM, suggesting that ISG20 may be a good marker in both viral prevention and cancer progression in patients with these types of cancer." (PMID 36177004, 2022). "Altogether, this study highlighted the value of combating cancer by targeting ISG20 during the COVID-19 pandemic, and small molecules extracted from traditional Chinese medicines, such as CD, may have potential as anti-SARS-CoV-2 and anticancer agents by promoting ISG20 expression." (PMID 36177004, 2022). "Interestingly, both CD and m62A increase ISG20 expression in various cancer cell lines, even though it is unknown whether CD and m62A regulate ISG20 expression by modification of DNA methylation patterns." (PMID 36177004, 2022). "On the other hand, the expression levels of ISG15, IFI27, OASL, ISG20, and DDX58 were lower in CDDP-R cancer cells than in parent cancer cells, which were consistent with the transcriptome profiling data." (PMID 37174688, 2023). "The results showed that high expressions of ISG15, IFI27, OASL, CCL5, ISG20, IFIT3, and other 21 ISGs were significantly correlated with improved OS rates in cancer patients receiving ICB therapy." (PMID 37174688, 2023). "The results of RT-qPCR verified that KU55933 significantly upregulated additional ISGs including ISG20, DDX58, DDX60, CCL5, and IFIT3 in CDDP-R cancer cells." (PMID 37174688, 2023). "Thus, high ISG20 expression in cancer may prevent viral invasion in these cancer patients." (PMID 36177004, 2022). "We also found significant correlations between ISG20 expression and immune lymphocytes, chemokines, receptors, immunoinhibitors, immunostimulators, and major histocompatibility complex (MHC) molecules in almost cancer types assessed." (PMID 36177004, 2022). "Isoforms ISG20-001 and ISG20−009 showed the same RNase_T domain structure, demonstrating the functional roles in tumorigenesis and SARS-CoV-2 invasion inhibition in cancer patients." (PMID 36177004, 2022). "Considering ISG20 inhibits viral replication and/or degradation, CD and m62A may play roles in preventing SARS-CoV-2 invasion and the severity of cancer." (PMID 36177004, 2022). "In accordance with a higher expression of KRAB-ZNFs in HFF/ISG20, a downregulation of extracellular matrix-related genes was observed, which recently have been suggested by Ito and colleagues to be suppressed by KRAB-ZNFs in various tumors leading to alterations of cancer phenotypes." (PMID 41511982, 2026). "Furthermore, ISG20 expression was significantly correlated with immune infiltration levels, including immune lymphocytes, chemokine, receptors, immunoinhibitors, immunostimulators, and MHC molecules in pan-cancer." (PMID 36177004, 2022). "Altogether, our study revealed the expression and distribution patterns of ISG20 in virus/SARS-CoV-2 invasion inhibition on different tissues and organs, differential expression and methylation patterns, and the prognostic significance across several types of cancer." (PMID 36177004, 2022).
musculoskeletal disease (1 paper, 2018). "Given the restriction observed with ectopic expression of ISG20 in MEFs, we sought to verify our findings in a mouse model of CHIKV infection and musculoskeletal disease (26, –, 28)." (PMID 30232164, 2018).
ISG20 also shares sentences with these, for which no sentence is quoted: melanoma (3 papers); acute myeloid leukemia (2); leukemia (2); oral cancer (2); astrocytomas (1); atherosclerosis (1); Autoimmunity (1); bacterial pneumonia (1); bovine respiratory disease complex (1); cervical disease (1); cervical tumours (1); endometriosis (1); Granuloma (1); H1N1 virus infection (1); hepatitis B (1); hepatitis C (1); kidney cancer (1); liver cirrhosis (1); lymphoma (1); medulloblastoma (1); meningioma (1); MRSA pneumonia (1); neurodegenerative disease (1); neurological disease (1); oligodendroglioma (1); osteoarthritis (1); prostate carcinoma (1); renal disorders (1); rhabdoid tumor (1); serous ovarian cancers (1).
A further 4 diseases each share a sentence with ISG20 in 1 paper.